CXCL12 (C-X-C motif chemokine ligand 12)
Diseases named in the same sentence as CXCL12 in open-access papers (continued):
Sharing a sentence is not in itself a finding about the gene and the disease.
cancer (continued). "The CXCR4/CXCL12 axis is key in mediating drug resistance in TNBC via a multi-pronged mechanism of action, including pro-survival signalling, induction of EMT, maintenance of cancer stem cells, immune suppression, and metastatic dissemination." (PMID 41002447, 2025). "Our results contribute to the theoretical foundation for novel therapeutic strategies that may involve targeting the CXCL12/CXCR4 pathway modulated by CAFs, with the ultimate goal of improving cancer outcomes across species." (PMID 40849508, 2025). "VEGF-A is highly expressed in macrophages and in cancer cells, and may induce MGP and atypical chemokine receptor ACKR3, which is a receptor of CXCL12." (PMID 41249124, 2025). "Thus, organosulfur components lower adipogenesis, adipose tissue inflammation, cancer development, and CCL2 and CXCL12 release." (PMID 40076892, 2025). "Enhanced levels of many cytokines related to cancer invasion and migration are found in the CMs of ET-1-treated cells, including IL-6, IL-8, CXCL11, and CXCL12, further supporting the hypothesis that ET-1 is a driver of activated fibroblasts." (PMID 38777849, 2024). "Cancer stem/progenitor cells overexpress the CXCR4 receptor, which transmits CXCL12 signals." (PMID 39070795, 2024). "Moreover, the significance of CXCL12 in the TME is explored by its interaction with CXCR4, which is often overexpressed in various cancers." (PMID 39070795, 2024). "Despite the well-established roles of CXCL12 and HMGB1 in cancer metastasis, the role of the CXCL12/HMGB1 heterocomplex has never been investigated." (PMID 38803493, 2024). "Understanding the relationship between the CXCL12/CXCR4/ACKR3 axis and the STAT3 pathway could lead to new therapeutic targets for innovative cancer treatments." (PMID 38920657, 2024). "Crosstalk between the CXCL12/CXCR4/ACKR3 axis and the STAT3 signaling pathway has been hypothesized on the basis of findings that both the CXCL12/CXCR4/ACKR3 axis and STAT3 signaling pathway are involved in the progression of several cancers." (PMID 38920657, 2024). "While CAFs-S1 stimulate cancer cell migration and initiate an EMT through CXCL12 and TGFB pathways, highly contractile CAFs-S4 induce cancer cell invasion in 3 dimensions via NOTCH signaling (NOTCH1, bSE = 3.0; NOTCH2, bSE = 2.6; NOTCH3, bSE = 1.4; NOTCH4, SE = 3.0)." (PMID 39335478, 2024). "They reported that DPP-4 inhibitors may promote cancer progression via induction of the CXCL12/CXCR4/mTOR axis, which is also important for vascular damage in cancer tissue." (PMID 39135967, 2024). "It was reported that the elevated levels of CXCL12 and reduced expression of its specific receptor in OC may be due to an enhanced capacity of CXCR4 receptors to bind a greater amount of CXCL12 in cancer patients." (PMID 38673838, 2024). "Furthermore, increased expression of chemokines CCL21 and CXCL12, and SDF1 was noted in the secretome from cancer tissue-derived MSCs." (PMID 39120301, 2024). "Also, in most of the cancers, there was a significant correlation between UBE2C gene expression and C10orf54, CXCL12, IL6R, MICB, PVR, THEM173, and TNFSF13." (PMID 38577722, 2024). "Importantly, it has been reported that a CXCR4 ligand, CXCL12, together with the CXCR4 receptor, plays a key role in cancer progression and metastasis." (PMID 38474372, 2024). "While the individual functions of CXCL12 and HMGB1 in cancer have been extensively explored, the role of the CXCL12/HMGB1 heterocomplex remains unclear." (PMID 38803493, 2024). "We investigated the effects of curcumin, a flavonoid known for CXCL12/CXCR4 axis inhibition, on breast TME by analyzing whether it can disrupt the ADMSC-cancer positive loop." (PMID 38004606, 2023). "Moreover, the inhibition of adenylate cyclase and consequent cAMP formation, induced by the CXCL12/CXCR4 complex, favors cancer cell proliferation." (PMID 37240258, 2023).
cancer (continued). "In addition, several reports have shown that the CXCL12/CXCR4 axis is involved in breast and prostate cancer cells’ metastasis to bone, where high expression of CXCR4, the receptor for the CXCL12 chemokine, is detected." (PMID 36826044, 2023). "We suspect that CXCL12 should be a tissue-specific chemokine, which cannot play its main function in EC, but this does not explain its important role in other cancers." (PMID 37352032, 2023). "CXCL12, also known as stromal cell-derived factor-1 (SDF-1), is an extracellular homeostatic chemokine that often binds to CXCR4, which could regulate cancer cell malignant progression." (PMID 38057830, 2023). "The signature genes CXCL2, CXCL12 and CX3CL1 were mainly expressed in cancer cells and monocytes." (PMID 37021054, 2023). "Although the anti-cancer activity of curcumin is widely studied, it is necessary to investigate its capacity to reshape the breast TME by modulating the intricate network of downstream signaling pathways related to the CXCL12/CXCR4 axis." (PMID 38004606, 2023). "The strict interaction between cancer cells and TME alters and damages the stromal structure leading to the release of signal proteins such as SDF-1 (CXCL12) and its receptor called CXCR4; the overexpression of these molecules is associated with cancer progression." (PMID 37627054, 2023). "Hence, CXCL12 and CXCR4 can be considered as key therapeutic targets for mBC to reduce the metastasis rate of cancer." (PMID 37497001, 2023). "For example, in the TME, the high levels of CXCL12, which binds its seven-transmembrane receptor, CXCR4, and the low levels of adiponectin may concomitantly contribute to mediating cancer cell growth and progression." (PMID 37240258, 2023). "The CXCL12/CXCR4 complex is a key factor in migration and survival of PCa cells, and indeed CXCR4 inhibitors induce apoptosis of the oncogenic cells and the suppression of cancer proliferation and vascularization." (PMID 36614308, 2023). "However, how oscillatory signals mediated by chemotactic molecules CXCL12 and EGF can be targeted with novel therapies in cancer remains incompletely understood." (PMID 36829763, 2023). "Through a variety of mechanisms, including the direct recruitment of MDSC, the synthesis of GM-CSF in oncogene-driven cancer cells, the stimulation of the epithelial-mesenchymal transition, and the production of VEFG and chemokines (such as CXCL12 and CXCR4), IL-17 exerts a pro-tumorigenic effect." (PMID 38139369, 2023). "In conclusion, the present exploratory study highlights that high CXCL12 TICs in OC are an independent positive predictive marker for chemosensitivity, OS, and RFS in primary tumors and prognostic for better overall survival in recurrent carcinoma." (PMID 37966614, 2023). "We hypothesize that a strong correlation of CXCL12/CXCR4 and CXCL12/pCXCR4 in recurrent carcinoma will arrest migratory immune cells." (PMID 37966614, 2023). "Comparing the migration rate of cancer cells with or without an EC monolayer towards CXCL12 over 24 hours, the authors discovered that MDA-MB-231 cells required at least 10 hours to cross the endothelium." (PMID 36439519, 2022). "Cancer cells in tumors containing control, scrambled small guide (sgScramble) PDA cells demonstrated staining with fluorochrome-conjugated antibodies to KRT20, KRT19, and CXCL12, respectively, and CD3+ T cells were infrequent in the areas of the KRT20+ cancer cells." (PMID 35046049, 2022). "The researchers found that after administration of AMD3100 for inhibition of chemokine (C-X-C motif) ligand 12 (CXCL12) receptor 4, T cells were rapidly recruited in cancer cells and acted synergistically with α-PD-L1 to dramatically reduce cancer cell proliferation and metastasis." (PMID 36046791, 2022). "Thus far, both CXCL12/CXCR4 and VEGF/VEGFR are the dominant pathways of EPC mobilization from bone marrow in cancer development." (PMID 35203510, 2022).
cancer (continued). "In the bone marrow, the chemokine CXCL12 (i.e., stromal-derived factor-1) recruits hematopoietic stem cells through its interaction with CXCR4 receptor (CD184), and this axis can be hijacked by cancer cells." (PMID 35158871, 2022). "Hence, this study aimed to investigate CXCL12, CXCR4, and FAPα and their value as cancer survival factors in LARC after nCRT." (PMID 34976180, 2022). "Olaptesed pegol (NOX-A12) is a PEGylated RNA Spiegelmer (L-ribonucleic acid aptamer) that specifically binds to the chemokine CXCL12 and inhibits the binding of CXCL12 to CXCR4 and CXCR7, thereby inhibiting the angiogenesis and metastasis from assisting the cancer treatment." (PMID 36393853, 2022). "We hypothesized that the expression profiles of CXCL12, CXCR4, and FAPα could provide valuable information regarding cancer invasion in LARC and cancer cell survival related to nCRT resistance in LARC." (PMID 34976180, 2022). "Furthermore, interaction of metastatic cancer cells with the hematopoietic niche is mediated by α4β1‐vascular cell adhesion molecule 1 (VCAM1), chemokines like CXCL12, BMP, Notch, Nestin, and osteopontin." (PMID 35506376, 2022). "CXCR4 activation promotes the migration of cancer cells towards CXCL12-expressing organs such as the lymph nodes, lungs, bone marrow and liver, which leads to the deposition of metastasis in these organs." (PMID 36140541, 2022). "CAFs also secrete CXCL12 (also known as stromal cell-derived factor 1, SDF1), which is a canonical ligand for the chemokine receptor CXCR4, to promote the growth and angiogenesis of CXCR4-expressing cancer cells." (PMID 35884382, 2022). "Nevertheless, this study establishes a previously unknown function of CXCL12 signaling to regulate PKM2 and glucose metabolism, connecting CXCR4 and ACKR3 to the metabolic adaptations of cancer cells." (PMID 35681470, 2022). "In response to CXCL12, CXCR4 and ACKR3 both recruit β-arrestin 2, regulating the assembly of interacting proteins that drive signaling and contribute to the functions of both receptors in cancer and multiple other diseases." (PMID 35681470, 2022). "Furthermore, it has been also demonstrated that CXCL12 and CXCR4 induce the activation of integrins which suggests a cooperation between the CXCL12–CXCR4 axis and the integrins in mediating cancer cell behavior, such as adhesion and survival." (PMID 35745762, 2022). "Cancer-associated fibroblasts differentiated monocytes into M2 macrophages by regulating the CXCL12/CXCR4 pathway, and then M2 macrophages could transform OSCC cells into cancer stem cell-like cells, which enhanced OSCC proliferation." (PMID 35693982, 2022). "CXCR4, its ligand CXCL12 and the atypical receptor ACKR3 are overexpressed in many human cancers." (PMID 36713377, 2022). "CXCL12/CXCR4 signaling induces the migration and stemness of cancer cells." (PMID 34927784, 2022). "The modeling procedure starts with presenting nonlinear dynamics of cancer cells and CAFs using ordinary differential equations based on TGFβ, CXCL12, and LIF signaling pathways." (PMID 36171274, 2022). "Thus, cross-linking CXCR4 by dimeric CXCL12 may elicit a “stop” signal that differs from the chemotactic signal stimulated by monomeric CXCL12 but may be similar to that elicited by the polymeric form of CXCL12 that is distributed on the surfaces of cancer cells." (PMID 35046049, 2022). "Since these two cell lines externalized KRT8 and KRT19, and the fetal calf serum in which they were cultured contained CXCL12, we determined whether the CXCL12–KRT19 coating could be formed in vitro by these cancer cells." (PMID 35046049, 2022). "Similarly, CXCL12/CXCR4 activation also increased MMP2/MMP9 and urokinase-type plasminogen activator expression by the Wnt/β-catenin pathway, enhancing cancer metastatic tendency." (PMID 36612163, 2022).
cancer (continued). "Paracrine production of growth factors and cytokines, including hepatocyte growth factor (HGF), insulin‐like growth factor (IGF), and stromal‐derived factor (SDF‐1/CXCL12) support a protumourigenic, chemotherapy‐resistant and immune‐suppressive environment in a variety of cancers." (PMID 35533046, 2022). "The CXCL12/CXCR4 biological axis plays a unique role in a variety of diseases and cancers." (PMID 35893797, 2022). "The CXCL12 chemokine is highly expressed in the lungs and attracts CXCR4-expressing cancer cells." (PMID 35203510, 2022). "The interplay between CXCL12 and CXCR4 induces the forming of metastasis cancers." (PMID 36211359, 2022). "In a later study OPN from cancer cells was found to stimulate the CAF myofibroblastic phenotype via ERK and Akt pathways that induced Twist1-dependent gene expression, leading to CXCL12 secretion, which ultimately promoted epithelial-to-mesenchymal transition (EMT) in cancer cells." (PMID 35378690, 2022). "However, immunosuppressive chemokines such as CXCL8, CXCL5, CXCL12, CCL2, and CCL22 were generally upregulated across the 13 cancer types." (PMID 34841742, 2022). "CXCL12 is a potent chemotactic factor that recruits macrophages, induces macrophages to release HE‐EGF and triggers anti‐apoptotic and proliferative signalling to promote cancer cell survival and expansion." (PMID 35363937, 2022). "In summary, our work establishes that CXCL12 signaling controls PKM2, a central regulator of metabolism in proliferating cells, and highlights the effects of CXCR4 and ACKR3 on metabolic reprogramming in cancer." (PMID 35681470, 2022). "Future research will determine the extent to which the CXCL12-dependent regulation of PKM2 through CXCR4 or ACKR3, either alone or in combination, controls the metabolic states of cancer cells relative to other downstream effectors, with established effects on the metabolism." (PMID 35681470, 2022). "Non-neoplastic epithelial cells and noninvasive carcinoma cells demonstrated little plasma membrane staining of either CXCL12 or CXCR4." (PMID 34976180, 2022). "In addition, EPI-X4 JM#21 showed increased efficiency for inhibition of CXCL12-mediated receptor signaling (>100-fold compared to EPI-X4, tenfold compared to WSC02) and cancer cell migration (~1500-fold compared to EPI-X4 and 30-fold compared to WSC02)." (PMID 34552197, 2021). "The identified real hub gene CXCL12 (stromal cell-derived factor 1) is an extracellular chemokine, which binds to CXCR4, a G-protein coupled receptor (GPCR) and have been well-recognized as a factor involved in the cancer metastasis." (PMID 34473751, 2021). "In addition, cancer-associated fibroblasts (CAFs) are able to secrete chemokines and cytokines, such as TGFβ, CXCL12, VEGF, and IL6, which stimulate cancer cell proliferation, epithelial–mesenchymal transition, and migration." (PMID 34868991, 2021). "This included decreased anti-inflammatory factors such as IL-4, IL-13, M-CSF and CXCL12 and antitumor factors SCF, FLT-3L and IL-25 that could contribute to cancer progression and metastasis." (PMID 34575976, 2021). "For the promoters of the CXCL12 and FAP genes, the transcripts of whose were detected specifically in IVP-9TS fibroblasts, an extremely low and nonselective promoter activity was shown both in IVP-9TS and in cancer cell lines." (PMID 33804861, 2021). "In summary, CXCL12 produced by the activated fibroblasts of the stroma-dense PDAC plays important roles in acquiring, maintaining, and enhancing several of the classical cancer traits in this difficult to treat malignancy." (PMID 35008248, 2021). "In cocultures of TNBC cells and BCAFs (both 2D and 3D), AMD3100 normalized cancer cell growth to the level observed in cells without any CXCL12 signaling." (PMID 34944738, 2021).
cancer (continued). "As abundant stromal cells in the TME, cancer-associated fibroblasts (CAFs) protect cancer cells from radiation-induced death and increase cancer cell radioresistance via paracrine action by cytokines, such as CXCL1, CXCL12, IGF1/2, and PDGF, eventually leading to RT failure and cancer progression." (PMID 34877934, 2021). "Among the many SASP factors, IL-6, CCL5, CXCL12, CCL2 and IL-8 have a particularly important role in supporting cancer cell metastasis formation and the establishment of an immunosuppressive microenvironment, although in some cancer models they can be found in the immune stimulatory secretome." (PMID 34079557, 2021). "In addition, the CXCL12-CXCR4 signal pathway composed of CXCL12 and its receptor CXCCR4 can promote the invasion and metastasis of many kinds of malignant tumors." (PMID 34930323, 2021). "Similarly, CXCL12 increased phosphorylation of p38 MAPK and SAPK in cancer cells co-expressing CXCR4 and CXCR7." (PMID 34298991, 2021). "In this primary culture, a unique transcription of the CXCL12 and FAP genes was observed; by pattern of gene expression, they corresponded to fibroblasts, and the SURV promoter of the cancer-specific gene Survivin (BIRC5) worked in it worse than in cancer cells." (PMID 33804861, 2021). "Moreover, CNP strongly decreases various cytokines secreted by CAFs are involved in cancer progression, such as IL-6, IL-8, C–C motif chemokine ligand 2 (CCL2), and CXCL12." (PMID 34284780, 2021). "As a result, CXCL12/CXCR4 axis plays a crucial role in cancer and could serve as a target for cancer therapy." (PMID 33962657, 2021). "The role of the CXCL12/CXCR4 axis in squamous cell carcinomas (SCC) has not been characterized to date with the same level of detail as in other types of cancer." (PMID 33530455, 2021). "Furthermore, 17β-estradiol supplementation increased mRNAs for CXCL12, TGFβ1, and LTBP1, predicting heightened immunosuppression, metastasis, and cancer stem cell activity." (PMID 34359625, 2021). "CAFs have been reported to be involved in cancer progression through the secretion of growth or pro-inflammatory factors, such as transforming growth factor-β (TGF-β), hepatocyte growth factor (HGF), and C–X–C motif chemokine ligand 12(CXCL12)." (PMID 34284780, 2021). "It has also been reported that IGF1/2, C-X-C motif chemokine ligand 12 (CXCL12; also called stromal cell-derived factor 1, SDF-1), and β-hydroxybutyrate secreted from CAFs induce autophagy in irradiated cancer cells and accelerate the recovery and regrowth of tumors after irradiation." (PMID 34135469, 2021). "Chemokine CXCL12 and its receptor CXCR4 are promising therapeutic targets for cancer management." (PMID 33456563, 2021). "Interestingly, CXCL12 secretion through osteocytes functions as a chemoattractant and helps in homing and retention of CXCR4 expressed cancer cells in the BM microenvironment." (PMID 34975909, 2021). "Moreover, CXCL16 produced by cancer cells binds to CXC receptor (CXCR) 6 on MSCs, leading to the transition of MSCs to CAFs and the production of CXCL12." (PMID 36046433, 2021). "Also, the transcriptional expressions of CXCLs family members were correlated with patients' individual cancer stages and nodal metastasis status, especially for CXCL2, CXCL3, CXCL4, CXCL7, CXCL9, CXCL10, CXCL11, and CXCL12." (PMID 32963527, 2020). "Thus, CXCL12 and its receptor CXCR4 were thought to represent a promising therapy targeting the link between cancer cells and stromal cells." (PMID 32972006, 2020). "In particular, the upregulation of CXCL12 (formerly known as Stromal derived factor 1, SDF-1) and of its cognate receptor CXCR4 significantly correlates with metastasis and poor cancer prognosis, as reported in a comprehensive review article by Wang and colleagues." (PMID 33233846, 2020).